FZD2 (frizzled class receptor 2)
Diseases named in the same sentence as FZD2 in open-access papers (continued):
Sharing a sentence is not in itself a finding about the gene and the disease.
ovarian carcinoma (1 paper, 2025). A malignant neoplasm originating from the surface ovarian epithelium. "In ovarian cancer, FZD2 has been implicated in extracellular matrix remodeling, a process critical for enabling metastasis." (PMID 40444048, 2025).
prostate adenocarcinoma (1 paper, 2025). "In contrast, FZD2 expression was notably reduced in kidney chromophobe (KICH), kidney renal clear cell carcinoma (KIRC), prostate adenocarcinoma (PRAD), and thyroid carcinoma (THCA)." (PMID 40444048, 2025).
prostate tumor (1 paper, 2018). "However, FZD2 mRNA levels were not upregulated in prostate tumor datasets and FZD2 did not co-localize with Wnt-11 in PC-3M cells." (PMID 29717114, 2018).
stomach adenocarcinoma (1 paper, 2025). "A particular focus on gastric adenocarcinoma – a major cause of global morbidity and mortality – reveals that FZD2 overexpression activates oncogenic pathways (Wnt/β-catenin and Notch) and induces EMT, thereby promoting metastasis and chemoresistance." (PMID 40444048, 2025).
tongue cancer (1 paper, 2019). A malignant neoplasm affecting the tongue. "Our in vitro studies confirmed that the downregulation of FZD2 expression effectively inhibits the proliferation of tongue cancer cells." (PMID 31595151, 2019). "In conclusion, we conclude that FZD2 acts as an oncogene in tongue cancer, promoting cell growth, invasion and migration." (PMID 31595151, 2019). "We analyzed the differential expression levels of FZD2 between clinical tongue cancer tissues and the adjacent tissues." (PMID 31595151, 2019). "Taken together, these results validate the finding that FZD2 promotes proliferation of tongue cancer cells in vitro." (PMID 31595151, 2019). "The overexpression of FZD2 in the tongue cancer cells clearly enhanced short-term cell growth as measured by the CCK8 assay." (PMID 31595151, 2019). "To further validate the carcinogenic effect of FZD2 in tongue cancer, we observed the changes in cell proliferation and migration in vitro and in vivo after altering the expression of FZD2 in tongue squamous cell carcinoma cells." (PMID 31595151, 2019). "The results showed that the expression level of FZD2 in tongue cancer tissues was higher than in the corresponding adjacent tissues (P<0.05)." (PMID 31595151, 2019). "To confirm the relationship between FZD2 and tongue cancer, we used real-time PCR to detect the expression of FZD2 in 44 pairs of tongue cancer tissues and their corresponding adjacent tissues." (PMID 31595151, 2019). "The results revealed that FZD2 plays an oncogenic role in tongue cancer and contributes to the migration and invasion of tongue squamous cell carcinoma cells." (PMID 31595151, 2019). "Taken together, these data suggest that the downregulation of FZD2 expression in tongue squamous cell carcinoma cells effectively inhibits the formation and growth of tongue cancer in vivo." (PMID 31595151, 2019). "The CCK8 and colony formation assays indicated that the siRNA-mediated knockdown of FZD2 significantly inhibited the growth of tongue cancer cells." (PMID 31595151, 2019). "To further investigate the effects of the FZD2 receptor binding to different WNT ligands in head and neck squamous carcinoma, we analyzed the coexpression of the FZD2 gene with 18 WNT ligands in the TCGA-HNSC dataset to systematically map FZD2-Wnt interactions in tongue cancer." (PMID 31595151, 2019). "The upregulation of FZD2 in clinical tongue cancer tissues was validated by real-time PCR." (PMID 31595151, 2019). "Collectively, these data suggest that FZD2 may contribute to carcinogenesis in tongue cancer." (PMID 31595151, 2019). "Therefore, we hypothesize that FZD2 may contribute to carcinogenesis in tongue cancer." (PMID 31595151, 2019). "Therefore, FZD2 may be a target for the diagnosis, prognosis and gene therapy of tongue cancer." (PMID 31595151, 2019). "Based on our analysis of the FZD2-WNT correlation, we speculate that FZD2 combined with different Wnt ligands will have different effects on the development of tongue cancer." (PMID 31595151, 2019).
tongue squamous cell carcinoma (1 paper, 2019). A squamous cell carcinoma that arises from the tongue. "Then, we silenced and overexpressed FZD2 in tongue squamous cell carcinoma cells to investigate changes in cell proliferation, migration, and invasion in vitro and in a nude mice xenograft tumor model." (PMID 31595151, 2019). "The purpose of the present study was to gain insight into the role of FZD2 in the cell proliferation and invasion of tongue squamous cell carcinoma." (PMID 31595151, 2019). "Furthermore, we also compared the expression of FZD2 between parental cells and highly metastatic cells of tongue squamous cell carcinoma." (PMID 31595151, 2019). "In this study, we aimed to illuminate the roles of FZD2 in tongue squamous cell carcinoma." (PMID 31595151, 2019). "In addition, our results demonstrate that the expression of FZD2 in tongue squamous cell carcinoma is higher than in the corresponding peritumoral tissue." (PMID 31595151, 2019). "We next investigated whether FZD2 could promote the migration and invasion of tongue squamous cell carcinoma cells." (PMID 31595151, 2019).
urothelial carcinoma (1 paper, 2024). A malignant neoplasm derived from the transitional epithelium of the urinary tract (urinary bladder, ureter, urethra, or renal pelvis). "We utilized a large dataset of urothelial carcinoma (UC) tumors to characterize non‐canonical WNT signaling through WNT5A, ROR1, ROR2, or FZD2 expression." (PMID 38558536, 2024). "The role of the WNT5A pathway (WNT5A, ROR1, ROR2, and FZD2) in the pathogenesis and progression of urothelial carcinoma (UC) has not been fully elucidated." (PMID 38558536, 2024).
uterine carcinosarcoma (1 paper, 2025). A usually aggressive malignant neoplasm arising from the uterine corpus and less often the cervix. "The highest alteration frequency of FZD2 was observed in uterine carcinosarcoma (UCS), with the predominant alteration type being ‘amplification’ (copy number alteration)." (PMID 40444048, 2025).
uveal melanoma (1 paper, 2025). A melanoma derived from melanocytes of the uveal tract. "Furthermore, analysis of disease-free survival (DFS) in the TCGA database indicated that higher FZD2 expression correlated with unfavorable outcomes in KIRC, LGG, MESO, STAD, and uveal melanoma (UVM), while lower FZD2 expression was linked to poorer DFS in GBM, LUAD, and THCA." (PMID 40444048, 2025).
tumor (41 papers, 2007 to 2025). "Despite these associations, systematic characterization of FZD2 through multi-omics approaches remains scarce, particularly regarding its interactions with the tumor microenvironment (TME), genomic instability, and drug response landscapes." (PMID 40444048, 2025). "FZD2 expression was correlated with various cancer characteristics, including stemness score, matrix score, immune score, tumor mutational burden (TMB), microsatellite instability (MSI), RNA modification genes, and drug sensitivity." (PMID 40444048, 2025). "We investigated the association between FZD2 expression and genomic heterogeneity metrics—including tumor purity, mutant-allele tumor heterogeneity (MATH), tumor mutational burden (TMB), and MSI-as potential biomarkers for immunotherapy response and prognosis." (PMID 40444048, 2025). "The impact of FZD2 on immune cell infiltration, tumor mutational burden (TMB), microsatellite instability (MSI), and drug resistance mechanisms supports its relevance in precision oncology." (PMID 40444048, 2025). "It was discovered that expressions of FZD2 and FZD6 (especially FZD2) were strongly and positively correlated with M2-type markers of tumor-associated macrophages (TAMs)." (PMID 36699699, 2022). "Many studies have shown that FZD2 is significantly associated with tumor development and tumor metastasis." (PMID 31595151, 2019). "Our data indicate that FZD2 promotes tumor growth in high-risk NBs by regulating β-catenin-dependent and –independent signaling pathways." (PMID 27323822, 2016). "Taken together, these data suggest that FZD2 blockade reduces tumor growth and tumor cell proliferation associated with decreased β-catenin levels and reduced angiogenesis in both, MYCN-unamplified SK-N-AS and MYCN-amplified SK-N-DZ NBs." (PMID 27323822, 2016). "Interestingly, high expression of ROR1, ROR2, and FZD2 were associated with a higher proportion of T cell‐inflamed tumor." (PMID 38558536, 2024). "Finally, FZD2 small interfering RNA knockdown suppressed tumor growth in murine NB xenograft models associated with suppressed β-catenin-dependent signaling and a less vascularized phenotype in both NB xenografts." (PMID 27323822, 2016). "Further investigations into FZD2’s interaction with immune checkpoints and its role in the tumor microenvironment will be invaluable for developing targeted therapies, especially in immune-resistant cancers." (PMID 40444048, 2025). "FZD2, a critical member of the Frizzled family, functions as a novel tumor marker and a pivotal receptor in Wnt signaling pathways, with specialized roles in non-canonical Wnt signal transduction." (PMID 40444048, 2025). "To clarify FZD2’s potential functions in tumor tissues, we analyzed its co-expressed genes in STAD using the LinkedOmics database." (PMID 40444048, 2025). "Both RT-qPCR and Western blot analyses consistently showed elevated FZD2 expression in tumor tissues." (PMID 40444048, 2025). "Gene set enrichment analysis (GSEA) was conducted to explore functional pathways, while a protein-protein interaction (PPI) network was constructed to further elucidate the role of FZD2 in tumor biology." (PMID 40444048, 2025). "Single-cell analysis further underscored the overexpression of FZD2 in fibroblasts within the tumor microenvironment." (PMID 40444048, 2025). "The robust associations between FZD2 expression and clinical outcomes, coupled with its functional implications in promoting tumor progression and influencing immune responses, underscore the potential of FZD2 in personalized medicine." (PMID 40444048, 2025). "Differences in FZD2 mRNA expression between tumor and normal tissues were analyzed using TIMER (TCGA RNA-seq data), revealing FZD2 overexpression in several cancer types." (PMID 40444048, 2025).
tumor (continued). "FZD2 meditates the EMT process and cell migration, and administering antibodies against FZD2 suppresses tumor growth and migration in animal models." (PMID 38167429, 2024). "Genes implicated in cell proliferation and migration such as Tgfβ3, Fzd2, Fzd9, and Lpar3 showed marked downregulation in tumor tissues post-FAA treatment." (PMID 38613073, 2024). "Orp treatment significantly inhibited the expression of WNT1, FZD2, β-catenin, and c-Myc compared to that in control tumor tissues." (PMID 38356709, 2024). "Fzd2 played a role in BC cell mesenchymal-like stemness; targeting Fzd2 inhibits tumor cell recurrence, metastasis, and chemoresistance." (PMID 36823639, 2023). "There is also a study reported that FZD2 suppresses tumor growth in salivary adenoid cystic carcinoma." (PMID 33832493, 2021). "FZD2 plays different roles in different tumors; even in the same tumor, the role of FZD2 can vary due to the different microenvironments within the tumor." (PMID 31595151, 2019). "On day 24, at which time the animals were sacrificed, the mean tumor weight was reduced by 49% in SK-N-AS bearing mice treated with FZD2 siRNA (1845 mg ± 546 mg) compared to control mice (3591 mg ± 572 mg; P < 0.001)." (PMID 27323822, 2016). "In any case, we conclude that the integration of the existing Wnt signals at the level of FZD2 promotes tumor growth in NBs." (PMID 27323822, 2016). "In contrast, the tumor tissue of FZD2 siRNA treated groups was more dense and homogeneous associated with reduced vessel density (left two panels)." (PMID 27323822, 2016). "Knockdown of Fzd2 or treatment with an anti-Fzd2 antibody reduced HCC tumor growth and metastasis in a mouse xenograft model." (PMID 27571105, 2016). "Along with the tumor suppression following FZD2 siRNA treatment, tissue FZD2 mRNA levels decreased in both NB xenografts (P < 0.02)." (PMID 27323822, 2016). "From a therapeutic perspective, FZD2 inhibitors, including small molecules targeting its bromodomain, may have the potential to enhance anti-tumor immunity when combined with immune checkpoint inhibitors (ICIs)." (PMID 40444048, 2025). "Of note, MN1 exerts a pro-tumor effect through the XIST/miR-15a-5p/MN1/FZD2 signaling axis, and its significantly high expression is observed in female patients with poor prognosis, which may be an important molecular basis for the gender difference in BLCA." (PMID 41019085, 2025). "FZD2’s involvement in cancer stem cells (CSCs) also complicates its role in tumor biology." (PMID 40444048, 2025). "The results demonstrated that FZD2 KO significantly suppressed tumor growth and reduced tumor size." (PMID 40444048, 2025). "Animal models were established to investigate the effect of FZD2 silencing on tumor growth." (PMID 33832493, 2021). "IHC showed that Ki-67 and TGF-β1 positivity was lower in tumor tissues of si-FZD2 group." (PMID 33832493, 2021). "Xenograft tumorigenicity assay was performed to assess the effect of FZD2 on tumor growth in vivo." (PMID 33832493, 2021). "As an oncogene, FZD2 can promote tumor cell proliferation, migration and metastasis." (PMID 33832493, 2021). "Despite the tumor-promoting function of WNT5a/FZD2 pathway was found in previous study, WNT5A is frequently silenced by promoter CpG methylation in ESCC, indicating that WNT5A may not be a critical ligand binding to FZD2 in ESCC progression." (PMID 32766155, 2020). "Functional experiments showed that LEF1-AS1 promotes the proliferation, migration, invasion and angiogenic ability of AIPC cells in vitro and tumour growth in vivo by recruiting the transcription factor C-myb to the promoter of FZD2, inducing its transcription." (PMID 33292271, 2020). "In addition, FZD2 is up-regulated in many types of cancers, which is considered to be a new predictor of tumor recurrence." (PMID 32766155, 2020).
tumor (continued). "Colony formation, transwell and tube formation assays were performed to assess whether FZD2 or CD44 knockdown could partly inhibit the tumour-promoting effect induced by LEF1-AS1 overexpression." (PMID 33292271, 2020). "The authors asserted that FZD2 may serve as a gene signature to predict tumor metastasis and overall survival in patients." (PMID 31595151, 2019). "Furthermore, FZD2 was considered likely to be a potential biomarker for tumor metastasis and a target for future therapies for this disease." (PMID 31595151, 2019). "Similarly, tumor masses in SK-N-DZ bearing mice (1928 mg ± 667 mg) were reduced by 43% in the FZD2 siRNA group compared with the control group (3366 mg ± 454 mg; P < 0.001)." (PMID 27323822, 2016). "Similarly, our study indicates that FZD2 may regulate tumor cell stemness through Wnt signaling, potentially contributing to chemoresistance." (PMID 40444048, 2025). "Notably, FZD2 expression was strongly correlated with M2 macrophage infiltration, suggesting that FZD2 may contribute to immune evasion, creating an immunosuppressive microenvironment conducive to tumor growth." (PMID 40444048, 2025). "However, high FZD2 expression was negatively correlated with tumor size (P < 0.05)." (PMID 32766155, 2020). "Cav1 might play an important physiological role in the defence against tumour‐derived exosomes via the degradation of Fzd2, thereby suppressing Wnt5a‐driven malignant transformation or inhibition of tumour‐derived exosomes internalization through an unidentified mechanism." (PMID 29502342, 2018). "Likewise, the effect of FZD2 blockade on angiogenesis was obvious at animal autopsy as the control but not FZD2 siRNA-treated tumors were quite hypervascular as seen in H&E-stained tumor tissue sections." (PMID 27323822, 2016). "Specifically, the FZD1, FZD2, FZD6, FZD7, and FZD8 genes were found to be significantly overexpressed in tumor tissues compared to normal pancreatic tissues, based on mRNA expression data from TCGA and other public databases." (PMID 40943055, 2025). "FZD2 and FZD6 play an important role in Wnt signalling, regulating epithelial–mesenchymal transformation (EMT) and tumour progression." (PMID 40045484, 2025). "Its interaction with FZD2 promotes cancer cell invasion, while suppression of ZEB1, a transcriptional regulator of Wnt5A, has been shown to reduce tumor cell proliferation and enhance apoptosis." (PMID 40943055, 2025). "Previous studies have shown that GRHL3 can inhibit tumor growth and development in ESCC, while NECTIN4 and FZD2 play a role as cancer-promoting genes in ESCC, and no relevant report has been made on the role of other genes in ESCC." (PMID 37653730, 2023). "In GEO cohort, AXIN1 and LEF1 were highly expressed in tumor tissues, while FZD4 and FZD2 were highly expressed in normal tissues." (PMID 36703749, 2022). "This article analyzes publicly available gene and protein expression data and reveals the existence of a WNT5A/FZD2/FZD7/ROR2 signature, which correlates with tumor-infiltrating and mesenchymal cell marker expression." (PMID 33869179, 2021). "Frizzled 2 (FZD2) is an important receptor in the Wnt pathway, which is highly expressed in malignant tumors and helps regulate multiple tumor behaviors." (PMID 33565732, 2021). "The tumor cells adapting to brain tissue do provide several pro-angiogenic functions temporarily, e.g. in BN25 15, Plxnd1, Vangl2, Fzd2, Fzd5, and Vegfa promote patterning of blood vessels and vascular development." (PMID 25004123, 2014). "Genes of this pathway up-regulated in CC tumor cells were JUN, MYC, FZD2, RAC1, GSK3B and CTNNB1, and a few others." (PMID 17822553, 2007). "A scatter plot analysis revealed a significant positive correlation between FZD2 and tumor purity in three cancers (GBM, THYM, TGCT) and a negative correlation in 16 cancers, including LUAD, COAD, BRCA, STES, STAD, and PRAD." (PMID 40444048, 2025).
tumor (continued). "This study compared the expression levels of miR-4516, Wnt 8B, FZD2, DVL3, FOSL1, CDK1, CDK2, CCNA1, and CCNB1 in primary LUAD tumor tissue with those in normal lung tissue using data from The Cancer Genome Atlas (TCGA) database to assess the consistency of our findings with the human sample." (PMID 38930863, 2024). "The results showed that FZD2 was heterogeneouslly overexpressed in tumor tissues and weakly expressed in non-tumor tissues." (PMID 32766155, 2020). "Four GPCRs were also over-expressed to a significant level within all three (WNT, SHH, Non-WNT/SHH) categorized tumor groups (FZD2, RPLP0, EDG4 and F2R)." (PMID 24252460, 2013). "The interaction between FZD2 and non-canonical Wnt ligands, such as Wnt5a, may vary across different cancer types, influencing its functional role in tumor progression." (PMID 40444048, 2025).